FZD2 (frizzled class receptor 2)
Description:
Receptor for Wnt proteins. Most of frizzled receptors are coupled to the beta-catenin canonical signaling pathway, which leads to the activation of disheveled proteins, inhibition of GSK-3 kinase, nuclear accumulation of beta-catenin and activation of Wnt target genes. A second signaling pathway involving PKC and calcium fluxes has been seen for some family members, but it is not yet clear if it represents a distinct pathway or if it can be integrated in the canonical pathway, as PKC seems to be required for Wnt-mediated inactivation of GSK-3 kinase. Both pathways seem to involve interactions with G proteins. May be involved in transduction and intercellular transmission of polarity information during tissue morphogenesis and/or in differentiated tissues. (Microbial infection) Acts as a receptor for C.difficile toxin TcdB in the colonic epithelium. TcdB occupies the binding site for Wnt-adducted palmitoleate in frizzled receptors and TcdB-binding prevents Wnt-binding and downstream Wnt signaling.
Synonyms: Fz-2; hFz2; Fz2; OMOD2; fzE2
Tractability: Small molecule: a structure with a bound ligand is known. Antibody: a drug acting on it is in phase 2 or 3 trials; its Gene Ontology location is reachable by antibodies, with high confidence; UniProt places it where antibodies can reach, with medium confidence; UniProt predicts a signal peptide or a membrane-spanning region. PROTAC: UniProt records ubiquitination sites on it; ubiquitination databases record sites on it; a small molecule that binds it is known.
Target class: Frizzled family G protein-coupled receptor; Membrane receptor
Gene: Protein-coding gene on chromosome 17 (44,557,484 to 44,561,262, forward strand). Ensembl gene ENSG00000180340.
Subcellular location: Membrane; Cell membrane
Subcellular location (Human Protein Atlas): Cell Junctions; Nuclear bodies; Nucleoplasm; Actin filaments; Basal body
Pathways (Reactome):
Signal Transduction: Asymmetric localization of PCP proteins; Ca2+ pathway; Class B/2 (Secretin family receptors); Disassembly of the destruction complex and recruitment of AXIN to the membrane; TCF dependent signaling in response to WNT; WNT5A-dependent internalization of FZD2, FZD5 and ROR2
Gene Ontology:
Molecular function: PDZ domain binding; protein binding; Wnt receptor activity; Wnt-protein binding; transmembrane signaling receptor activity
Biological process: canonical Wnt signaling pathway; positive regulation of DNA-templated transcription; Wnt signaling pathway; neuron differentiation; non-canonical Wnt signaling pathway; Wnt signaling pathway, planar cell polarity pathway; cell surface receptor signaling pathway
Cellular component: cytoplasm; focal adhesion; plasma membrane; clathrin-coated endocytic vesicle membrane; membrane
Genetic constraint (gnomAD): Loss-of-function variants: 18 observed, 38.68 expected, observed/expected ratio (o/e) 0.47, 90% interval 0.32 to 0.69. The upper end of that interval is the gene's LOEUF score, 0.69, which puts it in group 2 of 6, group 1 being the genes least tolerant of losing a copy. Missense variants: 525 observed, 800.42 expected, observed/expected ratio (o/e) 0.66, 90% interval 0.61 to 0.7. Synonymous variants: 333 observed, 351.86 expected, observed/expected ratio (o/e) 0.95, 90% interval 0.86 to 1.04.
Homologues: Orthologues: macaque FZD2 (100% identical), dog FZD2 (99% identical), mouse Fzd2 (99% identical), rat Fzd2 (99% identical), pig FZD2 (96% identical), chimpanzee FZD2 (96% identical), tropical clawed frog fzd2 (88% identical), guinea pig FZD2 (84% identical), zebrafish fzd2 (76% identical), Drosophila melanogaster fz3 (25% identical). Paralogues in human: FZD1 (79% identical), FZD7 (78% identical), FZD8 (50% identical), FZD5 (49% identical), FZD10 (45% identical), FZD4 (43% identical), FZD3 (43% identical), FZD9 (42% identical), FZD6 (42% identical), SMO (27% identical), SFRP4 (17% identical), FRZB (16% identical), and 3 more.
Diseases named in the same sentence as FZD2 in open-access papers:
FZD2 is named in the same sentence as 92 diseases in open-access papers, as found by Europe PMC text mining. Sharing a sentence is not in itself a finding about the gene and the disease. The quoted sentences say what the papers report.
breast cancer (12 papers, 2006 to 2025). A primary or metastatic malignant neoplasm involving the breast. "Other DEGs that were upregulated in the PTX-res cells included the β-tubulin encoding gene TUBB3, which has been associated with paclitaxel resistance and FZD2, a member of the Wnt receptor Frizzled family, which has been shown to endow breast cancer cells with drug resistance." (PMID 36078127, 2022). "The Frizzled 1 and 2 receptors (FZD1 and FZD2) are also overexpressed in breast cancer, and high β-catenin activity is significantly correlated with poor prognosis in breast cancer patients." (PMID 16933995, 2006). "FZD2 and its ligands Wnt5a/b (Wnt signaling pathway) were elevated in many cancers including breast cancer, and their expression correlated with epithelial–mesenchymal transition (EMT), which is a process that allows cancer cells to infiltrate surrounding tissues and metastasize to distant sites." (PMID 32053966, 2020). "FRIZZLED-2 (FZD2) was significantly expressed in all breast cancer cell lines and tissues examined." (PMID 24683528, 2013). "Our differential expression analysis revealed significant upregulation of FZD2 in cancers such as bladder cancer (BLCA), breast cancer (BRCA), cholangiocarcinoma (CHOL), and STAD, while it was downregulated in kidney cancers (KICH, KIRC)." (PMID 40444048, 2025). "Eight of these genes (except WNT2, GADD45B, FZD2, WNT7B, POLK, and PIK3R3) have been extensively studied in breast cancer." (PMID 32818022, 2020). "Knockout of Fzd2 significantly reduced the expression of ABC transporter subfamily G isoform 2 (ABCG2) and IC50 of paclitaxel, indicating that knockout of Fzd2 enhanced the sensitivity of breast cancer cells to paclitaxel." (PMID 41211430, 2025). "Furthermore, we tested the expression of FZD2, SFRP2, STK31, and LALBA proteins in canine mammary (CF41 and P114) and human breast cancer cells lines (HCC1500, T47D, DCIS.com, MDA231, and MCF7)." (PMID 32053966, 2020). "These patterns include elevated Fzd2 in metastatic breast cancer, increased ORAI1 in basal-like breast cancer (BLBC), high expression of Vangl2 and ROR1 in BLBC, and overexpression of Syndecan in BC generally." (PMID 40804731, 2025). "In addition, in metastatic liver, lung, colon and breast cancer cell lines, FZD2 drives the epithelial-mesenchymal transition (EMT) and cell migration through the non-canonical WNT5a/FZD2/STAT3 pathway." (PMID 32766155, 2020).
prostate carcinoma (10 papers, 2009 to 2025). A carcinoma that arises from epithelial cells of the prostate gland. "WNT5A is upregulated in prostate cancer and can promote tumor cell invasion through FZD2 and ROR246." (PMID 37524814, 2023). "This resulted in an increase in Fzd2/Wnt/β-catenin signaling by recruiting C-myc to upregulate Fzd2 transcription in prostate cancer." (PMID 34671643, 2021). "Genes encoding FZD2-5, FZD8, VANGL1, ROR1, RYK, LGR4, LRP5 and 6, and GPC4 were highly expressed in at least three prostate cancer cell lines." (PMID 29717114, 2018). "FZD4 expression was higher in androgen-independent and metastatic prostate cancer cell lines, while FZD2 was upregulated in hormone-depleted LNCaP cells, similar to WNT11." (PMID 29717114, 2018). "This analysis detected increased activation of NCWP through Wnt5a/ Fzd2 as the most common mode of Wnt activation in prostate cancer." (PMID 28030815, 2017). "Wnt5a promotes liver fibrosis by FZD2 and FZD8 42, and Wnt11 binds to FZD8 known to be involved in TGF-β signaling in prostate cancer." (PMID 33391533, 2021). "FZD4, FZD8, and PTK7, but not FZD2, were more highly expressed in prostate cancer than in benign or normal prostate tissue." (PMID 29717114, 2018). "Furthermore prostate cancer invasion has been described to depend on ROR2 and FZD2." (PMID 29930766, 2018). "A newly discovered NCWP, Wnt5/Fzd2, has been shown to induce epithelial-to-mesenchymal transition (EMT) in cancers, but has not been investigated in prostate cancer." (PMID 28030815, 2017).
gastric cancer (7 papers, 2019 to 2025). A primary or metastatic malignant neoplasm involving the stomach. "Many studies have shown that the abnormal expression of FZD2 is significantly associated with the development of many tumors, such as gastric cancer 12, hepatocellular carcinoma 13 and endometrial cancer 14, in which FZD2 plays oncogenic roles." (PMID 31595151, 2019). "In functional assays using gastric cancer cell lines, FZD2 knockdown significantly inhibited cellular proliferation, migration, and invasion." (PMID 40444048, 2025). "Western blot analysis of 8 paired gastric cancer samples further supported these results, showing increased FZD2 levels in tumor tissues." (PMID 40444048, 2025). "The prognostic significance of FZD2 was further validated using Kaplan-Meier analysis in GEO datasets, where gastric cancer patients with elevated FZD2 mRNA levels exhibited worse prognoses compared to those with lower levels." (PMID 40444048, 2025). "Specifically, high FZD2 expression was identified as a risk factor for overall survival (OS), first progression (FP), and post-progression survival (PPS) in gastric cancer patients (P < 0.05 for each)." (PMID 40444048, 2025). "A subcutaneous gastric cancer xenograft model was established in nude mice to investigate the effect of FZD2 knockdown on tumor growth in vivo." (PMID 40444048, 2025). "Extensive studies further demonstrate that FZD2 overexpression induces oncogenic phenotypes across multiple cancers, including glioma and gastric cancer." (PMID 40444048, 2025). "RT-qPCR validation of FZD2 mRNA expression in 39 paired gastric cancer tissues demonstrated higher expression in tumor tissues compared to normal tissues." (PMID 40444048, 2025). "FZD2 knockdown was demonstrated by both in vitro and in vivo experiments to suppress tumor cell proliferation, migration, and invasion in gastric cancer cell lines, indicating its critical role in tumor progression." (PMID 40444048, 2025). "The HPA database revealed that FZD2 is present in various cellular compartments, with increased FZD2 protein levels found in liver, pancreatic, and gastric cancer tissues compared to normal tissues." (PMID 40444048, 2025). "Additionally, apoptosis assays showed that silencing FZD2 increased the apoptotic rate in gastric cancer cells." (PMID 40444048, 2025). "In summary, our study identifies FZD2 as a significant pan-cancer biomarker, particularly in gastric cancer, where it may serve as a target for therapeutic interventions." (PMID 40444048, 2025). "Our data suggest that FZD2 could serve as a predictive biomarker for chemotherapy resistance in gastric cancer." (PMID 40444048, 2025). "The FZD2 level can be used to predict median overall survival (OS), the degree of immune cell infiltration, and the immune response of gastric cancer patients and to assess the effect of immunotherapy, with FZD7 expression suggesting a higher gastric cancer incidence and lymph node metastasis." (PMID 38952556, 2024). "In gastric cancer (GC), gene expression profiling highlighted FZD2’s significant role in tumorigenesis." (PMID 40444048, 2025). "FZD2 shRNA could suppress the proliferation, migration, and invasion of gastric cancer cells." (PMID 33618667, 2021). "As previously reported, FZD2 is dysregulated in various cancer types, such as oral squamous cell carcinoma (OSCC), gastric cancer (GC), endometrial cancer (EC), hepatocellular carcinoma (HCC) and tongue squamous cell carcinoma (TSCC)." (PMID 33832493, 2021). "WNT5A also induced gastric cancer migration and invasion by binding to FZD2 and ROR2, and treatment in vivo with anti-WNT5A antibody inhibited liver metastasis of gastric cancer cells." (PMID 33178184, 2020). "A total of 5 × 106 FZD2 knockout (KO) AGS and HGC-27 gastric cancer cells were resuspended in sterile PBS and mixed with Ceturegel® matrix gel before being subcutaneously injected subcutaneously into the flank area of 6–7-week-old male BALB/c-nude mice (n = 3 per group)." (PMID 40444048, 2025).
gastric cancer (continued). "WNT5A activates the nonclassical Wnt/Ca2+ pathway by binding to the FZD2 and promotes the invasion and migration of gastric cancer cells." (PMID 38952556, 2024). "FZD2 and FZD7 can be used as markers to assess the treatment and prognosis of gastric cancer patients and guide individualized treatment of patients with GC." (PMID 38952556, 2024). "The mRNA levels of RAI14, GUCY1A2, CNGB3, FJX1, FZD2, ELOVL2, and GDPD4 were all expressed upregulated in gastric cancer tissues, except for CXCL13, whose expression level was not significantly different between gastric cancer tissues and normal cell lines." (PMID 36823639, 2023).
glioma (7 papers, 2017 to 2025). A benign or malignant brain and spinal cord tumor that arises from glial cells (astrocytes, oligodendrocytes, ependymal cells). "Among these, FZD2 is a known prognostic marker for glioma progression, with its expression linked to tumor grade." (PMID 40430278, 2025). "Genes associated with the neuronal differentiation pathway (Pcsk9, Runx1, Cebpb, Fzd4, Wnt7a, Ascl1, Fzd2, Edn3, Olig2, and Gpc2), gliomas (Shc1, Cdk4, E2f2, and Ccnd1), and cell cycle (Bub1b, Bub, Ccnb1, Ccnb2, and Cdc20) were significantly downregulated." (PMID 36147849, 2022). "FZD1/2/5/6/7/8 could be an unfavorable prognostic factor in glioma and FZD2 and FZD6 may be novel independent predictors of poor prognosis in glioma." (PMID 36699699, 2022). "In summary, our preliminary findings revealed that FZD1/2/5/6/7/8 may be a disadvantageous factor for glioma, whereas FZD2/6 may serve as a novel independent predictor of poor prognosis." (PMID 36699699, 2022). "Collectively, our finding strongly demonstrated a crucial role of the FZDs in glioma and proved that FZD2 and FZD6 may be novel independent predictors of poor prognosis in glioma." (PMID 36699699, 2022). "Moreover, our findings confirmed that the high expression of FZD1/2/5/6/7/8 was a disadvantageous factor in glioma, while FZD2 and FZD6 could positively serve as independent predictors of poor prognosis." (PMID 36699699, 2022). "Taken together, these findings suggest that FZD2 and FZD6 may serve as independent predictors of poor prognosis in glioma, and FZD1/5/7/8 may be a disadvantageous factor." (PMID 36699699, 2022).
hepatocellular carcinoma (7 papers, 2014 to 2022). A malignant tumor that arises from hepatocytes. "For example, FZD2 was upregulated in the hepatocellular carcinoma and was significantly associated metastasis and cancer recurrence." (PMID 36776376, 2022). "FZD2 was over-expressed in hepatocellular carcinoma (HCC) and head and neck squamous cell carcinoma compared to paracancerous tissues and significantly associated with the survival of patients." (PMID 33618667, 2021). "In hepatocellular carcinoma, FYN-mediated activation of the STAT3 pathway plays an important role in Fzd2-driven EMT and the migration of liver cancer cells." (PMID 36498797, 2022). "FZD2 contributes to EMT via non-canonical signaling in hepatocellular carcinoma in vitro." (PMID 34604862, 2021). "Another study showed that FZD2 was expressed in tumorous HCC tissue but not in the surrounding nontumorous tissue and that the proliferative capacity of hepatocellular carcinoma cells was decreased after transfection with FZD2-targeting shRNA." (PMID 31595151, 2019).
liver fibrosis (6 papers, 2012 to 2022). "In particular, Wnt5a is involved in the liver degeneration, being overexpressed in liver fibrosis, which presents FZD2 and FZD7 as receptor." (PMID 35334792, 2022).
lung carcinoma (6 papers, 2014 to 2023). "For example, in patients with lung cancer, higher FZD2 expression was associated with improved survival; also, in patients with high-grade serous carcinoma after chemotherapy, the high level of FZD1 was associated with longer OS." (PMID 35178201, 2022). "In fact, Fzd2 and Wnt5a/b (among 10 Fzds and 16 Wnts) are known to be expressed at higher levels in several metastatic cancer cells, including lung cancer cells." (PMID 37703992, 2023). "For instance, it has been demonstrated that in the presence of WNT3a, FZD2 activates β-catenin-dependent signaling in lung cancer, while in melanoma cell lines, WNT5a/FZD2 signaling activates the non-canonical WNT/Ca2+ pathway." (PMID 32766155, 2020).
esophageal cancer (5 papers, 2020 to 2025). A primary or metastatic malignant neoplasm involving the esophagus. "Esophageal cancer specimens exhibit co-overexpression of Wnt2 and Wnt5A, as well as receptors such as FZD2 and FZD6, which are linked to worse prognosis and reduced survival." (PMID 40943055, 2025). "Moreover, Wnt5A/FZD-2 signaling could activate Src family kinases (SFKs) and induces cervical, lung, and esophageal cancer cell proliferation." (PMID 33723319, 2021).